CD14 (CD14 molecule)
Diseases named in the same sentence as CD14 in open-access papers (continued):
Sharing a sentence is not in itself a finding about the gene and the disease.
preeclampsia (7 papers, 2016 to 2025). Preeclampsia is a hypertensive disorder of pregnancy that is characterized by new-onset hypertension with proteinuria presenting after 20 weeks of gestation, and depending on mild or severe forms may initially present with severe headache, visual disturbances, and hyperreflexia. "In the decidua of patients with preeclampsia, the expression of CD14+, CD163+ and Macrophages was increased, and the number of Macrophages M2 with anti-inflammatory effect was decreased." (PMID 36541903, 2022). "In line with this conclusion, in women with preeclampsia a subset of decidual CD14+DC-SIGN+ APCs with reduced HLA-G and ILT4 expression and impaired ability to promote Tregs in vitro have been identified." (PMID 29686676, 2018). "The Mph, defined as CD14+ cells, in third-trimester decidua of women with preeclampsia were found to be decreased using immunohistochemical analysis, although this observation was not confirmed in another study where a bigger cohort was analyzed by FACS analysis." (PMID 27239344, 2016). "At the same time, in placental tissue in patients with preeclampsia, on the contrary, a significant decrease in regulatory cells CD4+, CD8+, CD14+, CD56+, CD59+, activation markers CD95+, as well as anti-inflammatory cytokine IL-10, growth factors VEGFR and IGF was detected." (PMID 40647643, 2025). "At the same time, in placental tissue in patients with preeclampsia, on the contrary, a significant decrease of regulatory cells CD4+, CD8+, CD14+, CD56+, CD59+, activation markers CD95+, as well as anti-inflammatory cytokine IL-10, growth factors VEGFR and IGF was detected." (PMID 40647643, 2025). "The authors speculated that the reduced IL-10 levels observed in preeclampsia may lead to reduced HLA-G and ILT4 expression and impaired tolerogenic activity of these CD14+DC-SIGN+ APCs." (PMID 29686676, 2018). "In the preeclampsia group, the statistically most significant differences were found for the following markers in peripheral blood: increased levels of CD16+, CD56+, HLA-DR+, CD95+, and intracellular production of cytokines—IL-10, TNF, Perforin, GM-CSF, IGF, while reducing CD14+ levels." (PMID 40647643, 2025). "Furthermore, another study elucidates a general change of CD14+/CD163+ or DC-SING/CD163+ (CD14+ and CD163+) Mph in the decidua basalis of women with preterm birth and preeclampsia in comparison with patients without preeclampsia." (PMID 27239344, 2016).
Sjögren’s syndrome (7 papers, 2013 to 2025). "TIGIT displays a scarce expression within a limited population of Nc-Mono cells, while decreased expression of TIGIT on CD14 + monocytes correlates with clinical features and laboratory parameters of patients with primary Sjögren’s syndrome." (PMID 38742110, 2024). "It has also been found that CEBPD is highly expressed in CD14(+) monocytes from patients with primary Sjogren's syndrome, and is involved in the TNF-α signaling pathway through NF-κB30." (PMID 38890389, 2024). "Additionally, a higher expression of type I IFN responsive genes was found in purified CD14+ monocytes from patients with Sjögren’s syndrome." (PMID 23637780, 2013). "Previously we found that MxA protein expression assessed using flow cytometry on CD14+ monocytes and a whole blood enzyme immunoassay are applicable biomarkers for systemic IFN-I activation in Sjögren’s syndrome." (PMID 29321042, 2018).
uveitis (7 papers, 2016 to 2025). An inflammatory process affecting a part of or the entire uvea. "Furthermore, Two cells were identified to be significantly associated with uveitis risk: HLA DR on in NK cells (OR = 0.938, 95%CI = 0.899 ~ 0.979, p = 0.003), HLA DR on CD14− CD16+ monocytes (OR = 0.924, 95%CI = 0.878 ~ 0.972, p = 0.002)." (PMID 39144656, 2024). "Accordingly, in this study, elevated frequencies of granulocytic CD11b+ CD14− CD15+ CD33+ (MDSC) were found in IAU patients during uveitis activity and might be linked to the increased presence of Th17 cells." (PMID 30105034, 2018). "In our study on immunophenotypes and their potential impact on uveitis, we identified two immunophenotypes that exhibit inhibitory effects against uveitis: HLA DR levels in NK cells and HLA DR on CD14− CD16+ monocyte." (PMID 39144656, 2024). "In uveitis, CD14++CD16+ monocytes are enriched in the circulation of patients with uveitis, when these patients are treated with glucocorticoids." (PMID 31877281, 2020). "PBMCs from 42 uveitis patients and 17 healthy donors were analyzed for CD14 and CD16 expression following a 48-hour culture in SFM without stimulation." (PMID 31729418, 2019). "HLA DR levels in CD14− CD16+ monocyte cells (OR = 0.735, 95% CI = 0.635 ~ 0.850, p < 0.001) and HLA DR levels in NK cells (OR = 0.910, 95% CI = 0.851 ~ 0.972, p = 0.005) were observed to be reduced in individuals with uveitis." (PMID 39144656, 2024).
acne (6 papers, 2010 to 2023). An inflammatory process of the sebaceous glands which is characterized by comedones, nodules, papules and/or pustules on the skin. "Mast cells appeared as pioneer cells in the acne immune response followed by the group of resident APCs (CD14+ dDCs, macrophages, cDC2s, cDC1s) and resident T cells." (PMID 34650562, 2021). "Furthermore, the capability of CD14 cells in acne patients to engulf P. acnes bacteria is impaired, but the introduction of exogenous IL-10 to PBMC cultures can reinstate phagocytic activity." (PMID 37894244, 2023). "It is tempting to speculate that locally activated commensal-specific TRM cells (in cooperation with local APC such as cDC2s, macrophages or CD14+ dDCs) drive the progression of the acne inflammatory process." (PMID 34650562, 2021). "Using a murine/human aGVHD gene signature we identified a cluster of ITGAX+CD14+S100A9+PTGS2+ macrophages that expanded in psoriatic but not acne skin compared with healthy controls." (PMID 35584681, 2022). "Acne inflammation may also develop because P. acnes stimulates the expression of TLR 2, 4 and CD14 in human keratinocytes." (PMID 20847936, 2010).
acute promyelocytic leukemia (6 papers, 2017 to 2022). An aggressive form of acute myeloid leukemia (AML), characterized by arrest of leukocyte differentiation at the promyelocyte stage, due to a specific chromosomal translocation t(15;17) in myeloid cells. "To determine if transcriptional machinery overlaps with H3K27ac signal, we utilized a Pol II ChIP-seq track (ENCODE) of NB4, a CD14+ acute promyelocytic leukemia cell line, with the H3K27ac ChIP-seq tracks of CD14+ WBCs." (PMID 34039742, 2021). "Moreover, EphA2 and EphA4 expression was induced, and ephrin-A4 expression was upregulated, in a human promyelocytic leukemia cell line, HL60, along with monocyte differentiation toward the classical CD14++CD16− monocyte subset." (PMID 28851287, 2017). "In acute promyelocytic leukemia (APL) patients, peripheral ‘group 2 innate lymphoid cells’ (ILC2s) were found to be increased and hyperactivated, and in turn activated M-MDSC (CD14+CD33+) through IL-13 secretion." (PMID 36304465, 2022). "In acute promyelocytic leukemia (APL) patients, tumor-activated ILC2s secreted IL-13 to induce M-MDSCs (CD33+CD14+HLA-DR-) and to support tumor growth, while ATRA treatment reversed the increase of ILC2-MDSCs in APL." (PMID 31640764, 2019).
amyotrophic lateral sclerosis (6 papers, 2012 to 2025). Amyotrophic lateral sclerosis (ALS) is a neurodegenerative disease characterized by progressive muscular paralysis reflecting degeneration of motor neurons in the primary motor cortex, corticospinal tracts, brainstem and spinal cord. "KLK1 is inhibited by several SMIs in the treatment of cardiovascular diseases 53, while the anti-CD14 antibody atibuclimab is administered to patients with amyotrophic lateral sclerosis." (PMID 41049426, 2025). "Increased numbers of blood CD14+CD16+ monocytes are observed in a number of viral and autoimmune disorders including rheumatoid arthritis, HAD, amyotrophic lateral sclerosis (ALS), Alzheimer’s disease, and some malignancies." (PMID 29538412, 2018).
Chagas disease (6 papers, 2016 to 2023). A parasitic infection caused by Trypanosoma cruzi. "Our working hypothesis was that CD14 functional polymorphism is associated with the clinical outcomes of human Chagas disease." (PMID 33146244, 2020). "Nevertheless, allele -260T on CD14 promoter might be a tag-SNP for cardiomyopathy severity in Chagas disease." (PMID 33146244, 2020). "In addition, using an in vitro system of T. cruzi infection, we observed that the parasite induces distinct responses in human CD14+ and CD14- monocyte subpopulations, which might be associated with the role of these cells during Chagas disease progression." (PMID 33146244, 2020). "Our previous studies documenting the design of a DNA vaccine consisting of pCDNA3 encoding TcG2 and TcG4 candidates that provided protection from Trypanosoma cruzi infection in mice and dogs have provided the proof-of-principle for further development of a vaccine against CD14–18." (PMID 38104118, 2023). "We observed an association between the T- genotype (absence of allele -260T) related to low CD14 expression and the dilated cardiomyopathy type of Chagas disease." (PMID 33146244, 2020). "Overall, our findings showed that T- genotype, related to polymorphism rs2569190 in CD14 gene, is associated with the dilated cardiac form of Chagas disease, but not with the non-dilated form, and may arise as a marker of susceptibility to disease severity." (PMID 33146244, 2020). "Only few studies in Chagas disease have characterized the phenotype of the monocyte subsets based on CD14 and the CD16 expression, finding an increase of CD14+ CD16+ monocytes percentage in asymptomatic children and adults during acute and chronic infection." (PMID 31379862, 2019). "In this context, CD14+CD56+ and CD3+HLA-DR+ were elected as the root attributes, as is consistent with the findings in human Chagas disease that highlight the robust role of macrophages and active T-cells as relevant biomarkers in the immune response triggered by T. cruzi infection." (PMID 26808481, 2016).
depression (6 papers, 2018 to 2025). "In patients with symptoms of anxiety/depression, the percentages of CD14 + + CD16 + monocytes and CD14 + CD16++ monocytes were higher, and the phagocytosis was decreased." (PMID 36906523, 2023). "For the elderly with some level of depression, triple-positive cells for CD14+CD80+CD86+ showed a decreasing trend (p = 0.0611)." (PMID 36193083, 2022). "An increase in TRAIL was observed in individuals with depression, in addition to an increased expression of CD14+CD86+." (PMID 36193083, 2022). "Key populations implicated include classical and non-classical monocytes (CD14, CD16), NK cell subsets (CD56, CD16), and granulocytes (CD15, CD16), all of which have been shown to be altered in individuals with depression, particularly in inflammation-associated subtypes." (PMID 41356500, 2025).
diffuse large B-cell lymphoma (6 papers, 2012 to 2023). "Comparative analysis among NHL types indicated the highest percentage of CD14+HLA-DRlow/− monocytes in patients with diffuse large B-cell lymphoma (DLBCL) comparing to follicular or indolent lymphoma." (PMID 36009726, 2022). "More recently, patients with diffuse large B-cell lymphoma (DLBCL) were found to have higher circulating CD14+ HLA-DRlo monocytic MDSCs, which was in concordance with two other studies." (PMID 30101129, 2018). "Similarly, in diffuse large B-cell lymphoma (DLBCL), neoplastic cells recruit T cells and CD14+ monocytes by CCL-5 release, also engendering a histiocyte-enriched microenvironment." (PMID 22400028, 2012). "In patients with diffuse large B-cell lymphoma, slan+CD16+ non-classical monocytes, but not CD14+ monocytes, increased and displayed highly efficient, rituximab-mediated, antibody-dependent cellular cytotoxicity, almost equivalent to that exerted by NK cells." (PMID 37835567, 2023).
emphysema (6 papers, 2004 to 2022). "Our findings, therefore, argue strongly for further studies on relationship between CD14 expression, AAT deficiency and increased susceptibility of PiZZ subjects to develop emphysema." (PMID 18426570, 2008). "Furthermore, we detected the upregulation of cd163 (marker of mature tissue macrophages) and cd14 (involved in development of Th1 response), as found in CS-induced emphysema." (PMID 35241086, 2022). "Although human lung macrophages are not known to express CXCR3, we suspected based on the immunohistochemical localization of this chemokine receptor that CD14+ cells in the lungs of ex-smoker individuals with emphysema accounted for much of the total lung CXCR3+ immunoreactivity (data not shown)." (PMID 15526056, 2004). "We have previously found that elevated plasma levels of soluble CD14 (sCD14), a marker of monocyte activation, were associated with emphysema in HIV+ but not HIV- subjects, supporting a potential role of immune activation in the development of emphysema among those with underlying HIV." (PMID 28122034, 2017). "We found that over 40% of CD14+ cells from participants with emphysema but not control participants were also positive for CXCR3." (PMID 15526056, 2004).
Ewing sarcoma (6 papers, 2007 to 2025). A small round cell tumor that lacks morphologic, immunohistochemical, and electron microscopic evidence of neuroectodermal differentiation. "TGFB1 expression is highest in NK cells, CD4+ T regulatory cells, CD8+ T cells, and CD14+CD16− monocytes isolated from human Ewing tumors." (PMID 40858520, 2025). "In vivo treatment of Ewing tumor-bearing mice with NOA2 results in a tumoral infiltrate of morphologically activated mouse CD14+ cells and an increase in human CD33+ cells." (PMID 38534214, 2024). "Mononuclear osteoclast precursors were found in the CD14+ (macrophage) population of cells isolated from Ewing's sarcomas and these cells were capable of differentiating into osteoclasts capable of lacunar resorption in the presence of RANKL and M-CSF." (PMID 17533390, 2007). "When CD14+ monocytes were co-cultured with either Ewing's sarcoma-derived fibroblasts or bone stromal cells, in the presence of M-CSF, evidence of osteoclast formation was noted with formation of TRAP+ and VNR+ MNCs." (PMID 17533390, 2007). "Fibroblasts isolated from Ewing's sarcomas and bone stromal cells consisted almost entirely of spindle-shaped mononuclear cells, which did not stain immunohistochemically for CD99, CD14 or CD68 or VNR and TRAP." (PMID 17533390, 2007). "We found that TAMs isolated from Ewing's sarcoma did not express the osteoclast markers TRAP and VNR, but did express CD14, a monocyte/macrophage marker not expressed by osteoclasts." (PMID 17533390, 2007). "24-h cultures of Ewing's sarcoma mononuclear cells on glass coverslips in the presence or absence of RANKL and M-CSF did not express the osteoclast markers TRAP and VNR but strongly expressed CD14, a macrophage antigen which is known not to be present on osteoclasts." (PMID 17533390, 2007).
head and neck squamous cell carcinoma (6 papers, 2015 to 2025). A squamous cell carcinoma that arises from any of the following anatomic sites: lip and oral cavity, nasal cavity, paranasal sinuses, pharynx, larynx, and salivary glands. "In head and neck squamous cell carcinoma (HNSCC), the infiltration numbers of CXCR1/2+CD15+ PMN-MDSCs and CD14+ M-MDSCs with immunosuppressive function are significantly increased." (PMID 36131911, 2022). "Importantly, GPX4 expression was positively correlated with the expression levels of monocyte markers (CD14 and CD115) and M2 macrophage markers (VSIG4 and MS4A4A) both in ESCA and in head and neck squamous cell carcinoma (HNSC)." (PMID 34722530, 2021). "In another study, both CD14+ MDSCs and CD15+ MDSCs from the tumors of head and neck squamous cell carcinoma (HNSCC) patients suppressed NK cells activation." (PMID 34336860, 2021).
hepatitis B (6 papers, 2014 to 2022). "Therefore, increased extracellular dopamine due to drug use may also contribute to neuroinflammation in drug abusers infected with hepatitis B and C by increasing the accumulation of CD14+CD16+ monocytes within dopamine rich regions of the CNS." (PMID 25647501, 2015).
interstitial lung disease (6 papers, 2012 to 2026). A diverse group of lung diseases that affect the lung parenchyma. "In addition, single cell RNA sequencing analysis of tissue-resident CD14+ pulmonary macrophages demonstrated activated profibrotic signature with the elevated FN1 expression in SSc patients with interstitial lung disease." (PMID 34504485, 2021). "Similarly, activated CD45+/CD14+/CD11b+ macrophages, isolated from bronchoalveolar lavage fluid of interstitial lung disease patients, formed LYVE-1+/podoplanin+ vessel-like structures." (PMID 22946011, 2012). "CD14+, CD34+, and Col I+ spindle-shaped cells have been found in increased numbers in lungs of SSc patients with interstitial lung disease." (PMID 27158466, 2016). "In case of the human interstitial lung disease, CD68+/D2-40+ or CD14+/D2-40+ macrophages co-localized with the lymphatic endothelial layer of newly formed vessels in intra-alveolar fibrotic lesions at a rate of ~1.6 cells per millimeter of endothelium." (PMID 22946011, 2012). "Another study has reported circulatory macrophage (CD204+CD163+CD206+TLR4+CD80+CD86+) and monocyte (CD14+CD206+CD163+CD204+TLR4+CD80+CD86+) populations that expressed both M1/M2 markers in systemic sclerosis patients and in interstitial lung disease (ILD)." (PMID 35603185, 2022).
ischemia (6 papers, 2018 to 2023). A hypoperfusion of the BLOOD through an organ or tissue caused by a PATHOLOGIC CONSTRICTION or obstruction of its BLOOD VESSELS, or an absence of BLOOD CIRCULATION. "Both the HDL and LDL fractionated plasma EV CD14 protein was associated with stress-induced ischemia." (PMID 32704130, 2020). "The main finding is that 10 genes (Clec5a, CD14, Fgr, Hck, Anxa1, Lgals3, Irf1, Lbp, Ptx3, Serping1) may represent key molecular links underlying acute activation of immune cells in the hippocampus in response to experimental ischemia." (PMID 34944656, 2021). "CD14 and CystatinC protein levels were independent significant predictors of stress-induced ischemia in the LDL and the HDL subfraction and SerpinC1 and SerpinG1 protein levels in the HDL fraction." (PMID 32704130, 2020). "ERK5 signaling, shown to be associated with monocyte inflammation and pro-inflammatory cytokine production in models of infection and ischemia, was also upregulated in CD14 monocytes." (PMID 33363531, 2020). "The histological analysis of gastrocnemius muscles 7 days after the induction of hindlimb ischemia revealed that the mice treated with vehicle or cEVs were characterized by diffuse necrotic area and by an intensive inflammatory cell infiltration (CD14+ cells) in the injured muscle tissue." (PMID 30514962, 2018). "CD14 is a co-receptor for Toll-like receptor 4 (TLR4), both of which increase following microglia activation and play a role in the microglia response to ischemia after they are activated by endogenous damage associated molecular patterns (DAMPs) such as ATP released from dying neuron." (PMID 36721258, 2023). "Consistent with the results from the complete study cohort SC1 HDL, CD14 LDL and CC LDL remained significant adjusted predictors of stress-induced ischemia." (PMID 32704130, 2020). "One cluster (SAMC; Cd14, Apoe, Spp1, Lpl) was notably mainly present in brain parenchyma after ischemia and absent in the other compartments." (PMID 35177618, 2022).